CD47 (CD47 molecule)
Diseases named in the same sentence as CD47 in open-access papers (continued):
Sharing a sentence is not in itself a finding about the gene and the disease.
cancer (continued). "One of stratagems for cancer cell evasion is to increase the expression of CD47, a ubiquitously expressed cell surface receptor." (PMID 31931812, 2020). "Based on these results, we further analyzed the SIRPα expression in macrophages and CD47 in cancer cells from the indirect co-cultures, maintained for 72 h at 20% or 1% O2, before the direct contact with the CFSE-labeled cancer cells." (PMID 32231135, 2020). "Similar to cancer cells, all immune cells can upregulate their CD47 surface expression during infection." (PMID 32882841, 2020). "Blocking the CD47-SIRPα interaction using anti-CD47 antibodies sheds a new light on the cancer immunotherapy 18,37,38." (PMID 32226539, 2020). "In particular, cancer cells express CD47, a ‘don’t eat me’ signal that interacts with signal regulatory protein alpha (SIRPα) on macrophages to prevent phagocytosis." (PMID 32999291, 2020). "CD47 is overexpressed in various types of cancer, and its overexpression is correlated with poor prognosis in patients." (PMID 32775303, 2020). "In cancer biology, CD47 is an essential key anti-phagocytic molecule that provides “Don’t eat me” signals to evade the immune system for clearance." (PMID 32286430, 2020). "The presentation of “find-me/eat-me”-danger-associated molecular pattern (DAMP) molecules and the reduced expression of the “don't eat me” signals (PD-L1 and CD47) in the dying cancer cells trigger an immune response by the host and achieve complete remission." (PMID 32377203, 2020). "Therapeutic targeting of the CD47-SIRPα checkpoint has been most intensively explored in the context of cancer." (PMID 33162986, 2020). "This argues for a more specific targeting of CD47 at the site of the cancer cell, thereby possibly preventing inhibitory effects on neutrophils’ transmigration." (PMID 33105656, 2020). "CD47 is a transmembrane glycoprotein widely expressed on the surface of cancer cells, which, embedded on exosomes, limits their clearance by circulating monocytes." (PMID 32746880, 2020). "This study provides a proof-of-concept for achieving antitumor responses in a personalized manner by vaccination using cancer cells with antibody blocking or targeted deletion of CD47." (PMID 31996683, 2020). "There are many efforts in trying to target CD47 at different points in its signaling pathway for the purpose of cancer treatment." (PMID 32677994, 2020). "Different cancers have different levels of CD47 expression, however, cancers with higher CD47 expression are more resistant to phagocytosis and anti-CD47 immunotherapy." (PMID 32882841, 2020). "Similar to cancers, there is growing evidence that the inhibition of CD47/SIRPa interaction induces an antimicrobial effect during infections." (PMID 32882841, 2020). "Recent studies are trying to alleviate these challenges proving that CD47 targeting is a novel anti-cancer approach." (PMID 32677994, 2020). "Blocking CD47-SIRPα interaction induced the phagocytic cells to recognize and attack cancer cells and this response was augmented by adding rituximab (please see “Targeting of CD47-SIRPα using antibodies” section for more details)." (PMID 32677994, 2020). "Administration of CD47-blocking monoclonal antibodies has been investigated in multiple preclinical human cancer models, and is capable of producing CD8+ T cell-mediated antitumor responses." (PMID 32198351, 2020). "One study showed that HIF-1α-dependent expression of CD47 leads to decreased phagocytosis of tumor cells, which promotes cancer progression and immune evasion." (PMID 32775303, 2020). "Cancer cells can also hijack innate immune checkpoints including the CD47–signal regulatory protein alpha (SIRPα) phagocytosis checkpoint." (PMID 32645996, 2020). "Due to the increased surface expression of CD47 on cancer cells, anti-CD47 can selectively target a macrophages mediate phagocytosis and clearance." (PMID 32882841, 2020).
cancer (continued). "Other immune checkpoint inhibitors, such as CD47, inhibit the phagocytosis of cancer cells by binding to the signal regulatory protein α (SIRPα) receptor expressed on macrophages and DCs." (PMID 33178201, 2020). "Studies showed that CD47 blockade promotes macrophage reprogramming, which drives macrophage phagocytosis of cancer cells in xenograft mouse models." (PMID 32326073, 2020). "Mechanistically, TNFa-NFkB1-signaling pathway directly regulates CD47 expression suggesting that cancers can evolve to drive CD47 overexpression to escape immune surveillance." (PMID 32882841, 2020). "is another humanized IgG4 anti-CD47 antibody that inhibits CD47-SIRPα interaction and enabled phagocytosis in cancer cell lines, including hematological cancer cell lines, as well as in solid tumor xenografts." (PMID 32677994, 2020). "Biologics, including humanized CD47 monoclonal antibodies and decoy SIRPα receptors, that block the SIRPα-CD47 interaction, are currently being developed as cancer immunotherapy agents." (PMID 32240171, 2020). "DLBCL and FL cancer cells express a high level of CD47 with an antiphagocytic signal that allows them to evade the immune response." (PMID 32677994, 2020). "Previous studies have revealed that CD47 is overexpressed (approximately three-fold compared to healthy cells) on the plasma membrane of all human cancers and enables cancer cells to evade phagocytosis." (PMID 32370748, 2020). "CD47 has been shown to commonly overexpress on cancer cells, including hematologic malignancies and numerous solid cancers." (PMID 32012878, 2020). "Except for its role in cancer, CD47 is also reported to be involved in the pathogenesis of diet-induced obesity." (PMID 32226539, 2020). "Specifically, cancer cells have been shown to overexpress CD47, where it forms a complex with signal-regulatory protein α (SRP- α) on phagocytes and inhibits macrophage-mediated phagocytosis of the TNBC cells." (PMID 33256070, 2020). "The ‘don't eat me’ signal achieved through high expression of CD47 is important for the survival of cancer cells and can also be harnessed to increase the longevity of target cells." (PMID 31899582, 2020). "We analyzed expression levels of CD47 mRNA in two paired carcinoma tissues and adjacent normal tissues using qRT-PCR." (PMID 32984001, 2020). "CD47/SIRP-α-blocking antibodies enhance antibody-dependent cellular phagocytosis (ADCP) of cancer cells upon co-treatment with anticancer monoclonal antibodies." (PMID 30710089, 2019). "Synthetic receptors and the CD47/SIRPɑ axis provide an opportunity to bring the potential value of macrophages in cancer immunotherapy into play." (PMID 31183992, 2019). "Further, SLAMF7 expression on hematopoietic cancer cells was reported as a requisite for phagocytosis upon treatment with a CD47 blocking antibody." (PMID 30710089, 2019). "The combination of agents with capacity to inhibit the CD47-SIRPα interaction with Abs that block the PD-1-PD-L1 binding is a promising therapeutic approach for the treatment of a broad range of cancers." (PMID 31921125, 2019). "As a key anti-phagocytic axis, CD47-SIRPα connection transfers “don’t eat me” signal to macrophage and inactivates macrophage phagocytosis, rendering cancer cell resistant to host’s innate immune monitoring." (PMID 31829270, 2019). "Given that CD47 is an anti-phagocytic signal, strategies to increase pro-phagocytic signals on cancer cells can synergize with CD47 blockade." (PMID 32038992, 2019). "Correspondingly, over-expression of CD47 in some cancers can protect tumors from innate immune surveillance." (PMID 31632920, 2019). "CD47 mRNA expression was also negatively correlated with SLFN11 promoter methylation in some cancers." (PMID 31632920, 2019). "Our first goal is to discover small molecules that disrupt the CD47-SIRPα protein-protein interaction (PPI) and develop them into ligand-selective CD47 inhibitors for use as research tools and pretherapeutic lead compounds for numerous cancers." (PMID 31276567, 2019).
cancer (continued). "These humanized CD47-CAR T cells demonstrated specific killing of CD47+ cancer cells in vitro and it will be interesting to assess their efficacy in clinical trials." (PMID 30809507, 2019). "For instance, expression of LILRB1 on macrophages inhibited induction of cancer cell phagocytosis by a CD47-blocking antibody by direct binding to MHC class I and inhibition of macrophage activity, which was reversed by antibody-mediated blocking of LILRB111." (PMID 30710089, 2019). "In the current report, we aimed to further delineate the potential role of SLAMF7 expression on cancer cells for CD47-targeted and monoclonal antibody-based therapy in DLBCL." (PMID 30710089, 2019). "CD47 mAb cancer immunotherapies have been translated to the clinic and first-in-human Phase I/II clinical trials in patients are currently ongoing." (PMID 31695797, 2019). "With the advent of cancer immunotherapy, SIRPα/CD47 immunotherapy with an aim to activate the innate immune system has drawn tremendous interest in treating cancer patients." (PMID 31611550, 2019). "Two monoclonal antibodies have been developed to directly target CD47 in different types of cancer and were clinically tested as monotherapy or in combination with other monoclonal antibodies such as cetuximab and rituximab." (PMID 31426611, 2019). "In a pre-clinical syngeneic model using ovalbumin as a model antigen, anti-CD47 antibody-mediated phagocytosis of cancer cells by macrophages led to increased priming of CD8+ T cells." (PMID 32038992, 2019). "Substantial evidence has been provided that overexpression of CD47 by many cancer types is an important mechanism of resistance to phagocytosis." (PMID 31878087, 2019). "CD47 is expressed on cancer cells, which can bind to SIRPα on macrophages and serve as a “do not eat me” signal usually presented by normal blood cells; it enables cancer cells to evade immunosurveillance by macrophages or other phagocytes." (PMID 31655607, 2019). "CD47 is a novel macrophage immune checkpoint that plays a broad role in cancer immune evasion across multiple cancer types and particularly in myeloid malignancies." (PMID 32038992, 2019). "Participating in the bidirectional inhibitory signaling through both CD47 and its ligand SIRPα on macrophages, CD47 has been regarded as the first gene known to be a target for cancer immunotherapy common to all types of cancers." (PMID 31139022, 2019). "CD47 is an immunoglobulin family member protein overexpressed on the surface of many cancer types, including leukemias, lymphomas, and solid tumors." (PMID 30938231, 2019). "We concluded that our metal-based phagocytosis assay can be used to detect differential phagocytosis of cancer cells by macrophages and found that anti-CD47 opsonization increased phagocytosis by M1-like MDMs." (PMID 30760760, 2019). "Accordingly, CD47 is considered as a biomarker of several cancer, and its high expression can be used a poor prognostic factor." (PMID 31528120, 2019). "CD47 overexpression on cancer cells often enables them to escape phagocytosis via the interaction with CD172a receptor on macrophages." (PMID 31189095, 2019). "EGFR inhibition significantly reduced CD47 expression on the surface of pre-apoptotic cells, favoring more efficient engulfment of cancer cells by monocyte-derived dendritic cells." (PMID 32082304, 2019). "CD47 is overexpressed by human cancer cells, allowing them to evade macrophage-mediated phagocytosis." (PMID 30770827, 2019). "In triple-negative breast cancer cells, HIF-1α induced the expression of CD47, leading to cancer stem cell phenotype switch and cancer cell escape from phagocytosis, which was mediated by bone marrow-derived macrophages." (PMID 31540045, 2019). "Third, blockade of calreticulin led to complete abrogation of anti-CD47 antibody-mediated phagocytosis of cancer cells in vitro." (PMID 32038992, 2019).
cancer (continued). "Targeted blocking CD47-SIRPα interaction for engaging macrophages to attack cancer cells represents a potentially promising immunotherapeutic strategy." (PMID 31461846, 2019). "In fact, CD47 is overexpressed in various kinds of cancer cells, and its high expression level is positively correlated to poor prognosis." (PMID 31183992, 2019). "Upregulation of the calreticulin gene is an adverse prognostic factor as the dominant pro-phagocytic signal in diverse tumors and is correlated with increased CD47 expression in cancer cells." (PMID 30079703, 2019). "Considering this, a bispecific antibody recognizing both CD47 and a cancer-specific antigen, in this case CD19 for B cell lymphoma, has been generated." (PMID 30941125, 2019). "Another question is why macrophage aggregation is more frequent in cancer tissues with high CD47 expression?" (PMID 31528120, 2019). "A recently published mouse model illustrates the potential use in vivo of a chronically secreted nanobody from bacteria binding to CD47, which is an anti-phagocytic receptor often over-expressed in human cancer." (PMID 31370301, 2019). "In this respect, expression of the pro-phagocytic signal SLAMF7 on both macrophages and cancer cells was recently reported to be a requisite for CD47 antibody-mediated phagocytosis." (PMID 30710089, 2019). "As a protective mechanism to this pro-phagocytic stimulus, cancer cells upregulate CD47 to evade phagocytosis." (PMID 32038992, 2019). "Cluster of differentiation 47 (CD47, encoded by cd47 in mouse) is a signaling receptor for thrombospondin-1 (TSP1) and an attractive cancer therapeutic target as blocking CD47 signaling protects normal tissue while sensitizing tumors to ionizing radiation." (PMID 31597291, 2019). "Disrupting the interaction between CD47 and SIRPα on cancer cell surface by blockade or down-regulation of CD47 efficiently promoted phagocytosis by macrophages in vitro and in vivo." (PMID 31139022, 2019). "As expected, the CD47 transcriptional downregulation negatively affected the phagocytosis of cancer cells by microglia." (PMID 31921125, 2019). "The cluster of differentiation 47/signal regulatory protein alpha (CD47/SIRPɑ) axis plays a critical role in inhibiting the activation of macrophages against cancer." (PMID 31183992, 2019). "One of the genes that showed consistent down-regulation in CD47-deficient cells was schlafen-11 (SLFN11), which in human cancers is positively correlated with sensitivity of cytotoxic agents including topoisomerase inhibitors." (PMID 31632920, 2019). "CD47 was expressed on the surface of all cancer cells analyzed, and CD47 blockade resulted in activation of anti-cancer activity from macrophages and eradication of tumors in mice." (PMID 31695797, 2019). "Preventing the binding between SIRPα and CD47 by B6H12 antibodies enhances cancer cell killing by immune cells." (PMID 30814491, 2019). "SIRPα and its ligand CD47 are expressed in humans and SIRPα-CD47 interaction has been targeted to treat human cancer." (PMID 31883525, 2019). "A recent study reported that the solution of anti-CD47 antibody-conjugated calcium carbonate NPs (anti-CD47@CaCO3) can modulate the immune response via blockade of CD47 as well as inducing phagocytosis of cancer cells." (PMID 31754376, 2019). "The CD47 is responsible for the production of membrane proteins increasing the survival of cancer cells by helping them to evade macrophage phagocytosis." (PMID 31345216, 2019). "CD47 is a prominent new target in cancer immunotherapy, with antagonistic antibodies currently being evaluated in clinical trials." (PMID 30710089, 2019). "This has led to the development of therapeutic antibodies and decoy molecules that inhibit the CD47-SIRPα interaction and their entry into multiple clinical trials for cancer patients as potential innate immune checkpoint inhibitors." (PMID 31632920, 2019).
cancer (continued). "CD47 is a “don't eat me” signal, which prevents cancer cells from phagocytosis by binding to signal regulatory protein alpha on macrophages." (PMID 30938231, 2019). "CD47 is overexpressed in most cancer types and was shown to promote cancer cell invasion and metastasis." (PMID 31426611, 2019). "It has been shown that CD47 is expressed in cancer-initiating cells and that this receptor is involved in metastasis progression." (PMID 30814491, 2019). "Since then, CD47 has been shown to be overexpressed in multiple hematologic and solid tumor malignancies and appears to be a universal signal by which cancer cells evade the innate immune system, and specifically macrophage phagocytosis." (PMID 32038992, 2019). "It is important to note that while CD47 is expressed on most cancers, it is also expressed on most normal cells." (PMID 32038992, 2019). "It recognizes CD47, which acts physiologically as a “don’t eat me” signal and is found to be ubiquitously overexpressed on many different types of cancer." (PMID 31805946, 2019). "CD47 has been considered as a biomarker of several carcinomas, and its high expression is also a poor clinical prognostic factor." (PMID 31528120, 2019). "We analyzed control and ADH1B overexpressing cells with qRT-PCR for the expression of such genes and found that ADH1B overexpression increases CD44 and CD47 expression in the cancer cells (p < 0.001 and p < 0.001)." (PMID 29861857, 2018). "The sharing of this mechanism with PrCR of non-malignant cells opens the path to testing therapies for disease cells protected by CD47, including a wide range of human cancer cells, atherosclerotic cells, and fibrotic disease cells." (PMID 30097573, 2018). "Through overexpression of CD47 on their surface, cancer cells defend themselves against phagocytosis by macrophages." (PMID 30062558, 2018). "Blockade of CD47 on cancer cells leads to their recognition and phagocytosis via a cell surface form of the effector calreticulin (CRT) on macrophages." (PMID 30097573, 2018). "Although CD47 expression protects some normal cells from being phagocytosed, CD47 transcript and protein expressions are also seen, and in some cases to a higher degree, in cancer cells to protect themselves from being phagocytosed." (PMID 30463284, 2018). "Inhibition of the CD47-SIRPA ‘Don’t eat me’ signaling pathway has also been shown to result in engulfment of cancer cells." (PMID 29862966, 2018). "We have shown elsewhere that cancer cells that are CD47+ can be phagocytosed in the presence of CD47 blocking antibodies, but only if the cells have displayed “eat me” signals such as CRT64." (PMID 30097573, 2018). "Virtually expressed in all types of cancers, CD47 is a transmembrane molecule that engages with signal regulatory protein-α (SIRPα) on the dendritic cells and macrophages." (PMID 30062558, 2018). "In all types of cancer, CD47 transcript and protein expression is abnormally upregulated, thus protecting the cancer cells from being recognized and eliminated by macrophages." (PMID 30213113, 2018). "CD47 hampers the “eat me signal” on cancer cells by interacting with SIRP on macrophages impairing phagocytosis." (PMID 30301213, 2018). "The binding of the cancer cell’s CD47 to the macrophage’s SIRPα receptor leads to SHP-1 and/or SHP-2 activation." (PMID 30097573, 2018). "Since IgG2 subclass of anti‐CD47 mAb was used in this study, biding anti‐CD47 mAb to CD47 on inoculated cancer cells theoretically promotes opsonizing effects via Fcγ/Fcγ receptor pathway." (PMID 30460349, 2018). "Recent paper of macrophage therapy introduces the antibody-blocking of SIRP-alpha inhibited CD47 interaction of macrophages on cancer cells which improves phagocytic uptake and removal of cancer." (PMID 30680249, 2018). "Overexpression of CD47 in cancer cells activates SIRPα, which is an inhibitory receptor expressed mainly by myeloid cells." (PMID 29988496, 2018).